RNU6-333P (RNA, U6 small nuclear 333, pseudogene)
Gene: Small nuclear RNA gene on chromosome 12 (53,138,545 to 53,138,651, reverse strand). Ensembl gene ENSG00000238669.
Homologues: Orthologues: chimpanzee U6 (97% identical), macaque U6 (96% identical), mouse Gm24149 (93% identical), mouse Gm25186 (90% identical), pig U6 (84% identical). Paralogues in human: RNU6-144P (93% identical), RNU6-20P (93% identical), RNU6-38P (93% identical), RNU6-16P (92% identical), RNU6-25P (92% identical), RNU6-574P (92% identical), RNU6-1 (91% identical), RNU6-1145P (91% identical), RNU6-1179P (91% identical), RNU6-1316P (91% identical), RNU6-2 (91% identical), RNU6-21P (91% identical), and 1291 more.